CRKL (CRK like proto-oncogene, adaptor protein)
Description:
May mediate the transduction of intracellular signals.
Tractability: PROTAC: ubiquitination databases record sites on it; its protein half-life has been measured.
Gene: Protein-coding gene on chromosome 22 (20,917,407 to 20,953,747, forward strand). Ensembl gene ENSG00000099942.
Subcellular location (Human Protein Atlas): Nucleoplasm; Cytosol
Pathways (Reactome):
Signal Transduction: Downstream signal transduction; Erythropoietin activates RAS; Frs2-mediated activation; MET activates RAP1 and RAC1; MET receptor recycling
Immune System: Regulation of signaling by CBL
Gene Ontology:
Molecular function: cadherin binding; identical protein binding; phosphotyrosine residue binding; protein binding; RNA binding; RNA polymerase II-specific DNA-binding transcription factor binding; receptor tyrosine kinase binding; signaling adaptor activity
Biological process: cellular response to transforming growth factor beta stimulus; negative regulation of gene expression; negative regulation of SMAD protein signal transduction; positive regulation of cell population proliferation; positive regulation of ERK1 and ERK2 cascade; positive regulation of glial cell migration; positive regulation of substrate adhesion-dependent cell spreading; cell migration; enzyme-linked receptor protein signaling pathway; intracellular signal transduction; JNK cascade; Ras protein signal transduction; cellular response to growth factor stimulus; positive regulation of Rac protein signal transduction; postsynaptic specialization assembly; regulation of cell migration; regulation of gene expression
Cellular component: nucleoplasm; cytoplasm; cytosol; extrinsic component of postsynaptic membrane; neuromuscular junction; protein-containing complex; synapse
Genetic constraint (gnomAD): Loss-of-function variants: 3 observed, 24.53 expected, observed/expected ratio (o/e) 0.12, 90% interval 0.055 to 0.32. The upper end of that interval is the gene's LOEUF score, 0.32, which puts it in group 1 of 6, group 1 being the genes least tolerant of losing a copy. Missense variants: 256 observed, 420.53 expected, observed/expected ratio (o/e) 0.61, 90% interval 0.55 to 0.68. Synonymous variants: 188 observed, 172.62 expected, observed/expected ratio (o/e) 1.09, 90% interval 0.97 to 1.23.
Gene-disease validity (ClinGen):
ClinGen rates the evidence that CRKL causes each of these diseases.
congenital heart disease (inheritance undetermined): No Known Disease Relationship. A heart disease that is present at birth.
Homologues: Orthologues: chimpanzee CRKL (100% identical), dog CRKL (97% identical), guinea pig CRKL (97% identical), mouse Crkl (97% identical), rabbit CRKL (97% identical), pig CRKL (96% identical), tropical clawed frog crkl (88% identical), rat Crkl (85% identical), zebrafish crkl (83% identical), Drosophila melanogaster Crk (43% identical), Caenorhabditis elegans ced-2 (31% identical). Paralogues in human: CRK (61% identical).
Diseases named in the same sentence as CRKL in open-access papers:
CRKL is named in the same sentence as 94 diseases in open-access papers, as found by Europe PMC text mining. Sharing a sentence is not in itself a finding about the gene and the disease. The quoted sentences say what the papers report.
breast carcinoma (27 papers, 2009 to 2024). "In this study, CrkL expression levels in the tumor tissue were associated with breast cancer growth and progression." (PMID 31323992, 2019). "Over-expression of Crk-like protein (CrkL), an intracellular adaptor protein, in breast cancer biopsies has been linked to poor prognosis." (PMID 31323992, 2019). "While the overexpression of CrkL in the tissue has been previously linked to breast cancer progression, we believe that this is the first report to evaluate the soluble fractions of CrkL in cell culture media and blood sera from breast cancer patients." (PMID 31323992, 2019). "CRKL has been found to have a prominent ability to promote cell proliferation and metastasis in malignant tumors such as breast cancer and cervical cancer." (PMID 37894400, 2023). "In this study, we demonstrated that CRKL controls breast cancer cell EMT by elevating Snail1 and N-cadherin protein levels and decreasing E-cadherin expression." (PMID 37894400, 2023). "In vivo, mice injected with miR-429-transfected breast cancer cells had reduced cancer-induced osteolysis when compared to a control, and histological analysis of the bone metastases showed a reduction in both CrKL and MMP-9 expression in the miR-429 group." (PMID 35158995, 2022). "The top 8 cancer types with 10 and higher cases of CRKL transcript amplification include lung cancer, melanoma, breast cancer, ovarian cancer, soft tissue sarcoma, bladder cancer, head and neck cancer, and sarcoma." (PMID 33801580, 2021). "Ablation of CrkII, CrkI, and CrkL altogether suppressed anchorage-independent growth of MDA-231 breast cancer cells." (PMID 33801580, 2021). "Previous studies reported that CRKL enhances malignancy of the cancers such as glioblastoma, breast cancer, and colon cancer." (PMID 33094104, 2020). "Studies have suggested that CRKL contributes pivotal roles in malignancy of human cancers such as glioblastoma, breast cancer, and colon cancer, among others." (PMID 33094104, 2020). "The data suggest that soluble fraction of CrkL can be further evaluated as a serum biomarker for advanced disease in breast cancer patients." (PMID 31323992, 2019). "Expression of CrkL and secreted fractions from human breast cancer cell lines and clinical patient samples were assessed by immunohistochemistry and Enzyme Linked Immuno-Sorbent Assay (ELISA)." (PMID 31323992, 2019). "In this study, we evaluated, for the first time, the levels of soluble CrkL in serum of breast cancer patients." (PMID 31323992, 2019). "The levels of CrkL in the breast cancer cell media were significantly higher than in the normal breast epithelium cell media." (PMID 31323992, 2019). "Further, to confirm the membranal fraction of CrkL, breast cancer cells were immunostained and analyzed by fluorescent microscopy." (PMID 31323992, 2019). "CRKL is overexpressed in a number of types of human malignant tumors, including cervical cancer, lung cancer, breast cancer, gastric cancer, and pancreatic carcinoma." (PMID 31133010, 2019). "The main objective of the present work was to evaluate the possibility of detecting secreted CrkL as a soluble biomarker in breast cancers, as well as to correlate serum levels of CrkL to various clinical parameters." (PMID 31323992, 2019). "Immunofluorescence staining of breast cancer cells revealed CrkL both on the cell surface and in the intracellular compartments." (PMID 31323992, 2019). "In conclusion, in this study, we have shown that high levels of secreted CrkL can be detected in the serum of breast cancer patients with advanced disease." (PMID 31323992, 2019). "For this purpose, we evaluated membrane-bound and secreted fractions of CrkL in human cancer cell lines and clinical tissue and blood serum samples from breast cancer patients with early and advanced disease, as well as healthy donors." (PMID 31323992, 2019).
breast carcinoma (continued). "The results of our study suggest that CrkL can be proposed as a soluble serum biomarker in breast cancer patients, especially in the advanced disease stages." (PMID 31323992, 2019). "For this purpose, we evaluated CrkL levels in human breast cancer cell line media in vitro, clinical breast cancer tissue and serum samples from breast cancer patients." (PMID 31323992, 2019). "MUC1 has also been implicated in cytoskeletal reorganization and cell motility through Src-CrkL-Rac1/Cdc42 signaling cascade following ICAM-1/MUC1 interaction in breast cancer cells." (PMID 24504508, 2014). "In breast cancer, CRKL and LASP1 were shown to be overexpressed and to correlate with tumor growth and progression." (PMID 24913448, 2014). "Using immunohistochemistry, we observed elevated CrkI/II and CrkL proteins in both high-grade tumors and proliferative breast cancers of the triple negative subtype, consistent with elevated Crk proteins being associated with aggressive breast cancer." (PMID 22569336, 2012). "CT10 regulator of kinase (Crk) adaptor proteins (CrkI, CrkII and CrkL) play a role in integrating signals for migration and invasion of highly malignant breast cancer cell lines." (PMID 22569336, 2012). "Stable knockdown of Crk (CrkI/CrkII/CrkL) proteins was accomplished using a short hairpin RNA (shRNA)-mediated approach in two basal breast cancer cell lines, MDA-231 1833TR and SUM1315, where the former have a high affinity to form bone metastases." (PMID 22569336, 2012). "CRKL induces cyclin D1 and phosphorylated extracellular signal-regulated kinase expression, overexpression of CRKL correlates with progression and malignant proliferation of human breast cancers." (PMID 36927310, 2023). "Moreover, hsa-miR-429 also directly targets and negatively regulates (v-crk sarcoma virus CT10 oncogene homolog (avian)-like) CRKL adaptor protein in breast cancer to promote cell migration and invasion." (PMID 37533517, 2022). "In addition, ablation of Crk by CRISPR/Cas9 inhibited in vivo growth of breast cancer cells, and ablation of both Crk and CrkL by CRISPR/Cas9 inhibited colorectal cancer cell adhesion, migration, invasion, and proliferation." (PMID 33561443, 2021). "Increased expression of both Crk and CrkL is reported in ovarian cancer and breast cancer tissues." (PMID 33801580, 2021). "In addition, knockdown of both Crk and CrkL in the breast cancer cell line resulted in defective lamellipodia formation and delayed cell spreading on fibronectin." (PMID 33801580, 2021). "Over-expression of CrkL in the tumor tissues has been reported in the numerous solid tumors, including prostate, gastric, hepatocellular carcinoma, lung, and breast cancers." (PMID 31323992, 2019). "Next, CrkL expression in clinical breast cancer specimens was evaluated." (PMID 31323992, 2019). "In the current work, we hypothesized that CrkL, generally considered as a protein overexpressed intracellularly in breast cancers, when secreted from the tumor cells, can possibly also serve as a serum biomarker for breast tumors." (PMID 31323992, 2019). "Serum levels of CrkL were significantly higher in breast cancer patients than in healthy donors." (PMID 31323992, 2019). "Considering that CRKL is important in proliferation, migration and evading apoptosis, we speculate that CRKL is probably essential in bone metastasis of breast cancer, however this needs further investigation." (PMID 25405387, 2015). "Based on these data, phosphorylation of CrkL on Y207 may serve as a biomarker for dasatinib response in breast cancer cells." (PMID 19513066, 2009). "As we summarized in our review, abnormal CRKL expression is associated with HCC, RCC, gastric cancer, glioblastoma multiforme, bladder cancer, lung cancer, colon cancer, ovarian cancer, leukaemia, breast cancer, head and neck cancer, rhabdomyosarcoma and neuroblastoma." (PMID 38683131, 2024).
breast carcinoma (continued). "In vitro studies revealed that in breast cancer CrkL plays a regulatory role in the stromal cell-derived factor 1 (SDF-1), induced Erk1/2, and phosphatidylinositol 3-kinase/Protein Kinase B (PI3K/Akt) pathways, which are directly linked to the invasion and migration of breast cancer cells." (PMID 31323992, 2019). "MiR-429 is probably involved in regulating the bone metastasis of breast cancer cells by targeting ZEB1 and CRKL." (PMID 35468721, 2022). "Others have shown that breast-cancer-cell-derived miR-429 reduces osteoclast differentiation in vitro via MMP-9 and V-crk sarcoma virus CT10 oncogene homolog-like (CrkL)." (PMID 35158995, 2022). "CrkL knockdown also inhibited cell proliferation in rhabdomyosarcoma, MDA-MB-453 breast cancer, MKN-45 gastric cancer, hepatocellular carcinoma, and HeLa cell lines." (PMID 33801580, 2021). "CRKL is a well‐documented oncogene in several types of cancers, including NSCLC,15, 16 gastric cancer 19 and breast cancer." (PMID 34076957, 2021). "Culture media from human breast cancer cell lines SUM159, MDA-MB231, and MCF7 showed over a 21-, 15-, and 11-fold higher concentration of soluble CrkL as compared to normal breast epithelium cell line MCF10A." (PMID 31323992, 2019). "CM from human breast cancer cell lines SUM159, MDA-MB231, and MCF7 showed over a 21-, 15-, and 11-fold higher concentration of soluble CrkL than CM from normal breast epithelial cell line MCF10A (545 ± 7, 393 ± 18, 289 ± 10 vs. 26 ± 5pg/mL, respectively)." (PMID 31323992, 2019). "Overexpression of CRKL may promote proliferation and invasion through the ERK signaling pathway in pancreatic cancer, breast cancer, small-cell lung cancer, gastric cancer, and myeloma." (PMID 38627856, 2024). "Elevation of CrkL protein level is also reported in non-small cell lung cancer (NSCLC), rhabdomyosarcoma, breast cancer, gastric cancer, thyroid cancer, ovarian cancer, cervical cancer, endometrial cancer, pancreatic ductal adenocarcinoma, and colorectal cancer tissues." (PMID 33801580, 2021). "Among ER+ breast cancers, 15% harbored FGFR1 gene amplification and/or mRNA overexpression whereas 2.5, 1.9, 2.4, and 1.7% harbored amplification and/or mRNA overexpression of CRKL, HCK, FRK, and FGR, respectively." (PMID 30914635, 2019).
gastric cancer (21 papers, 2011 to 2025). A primary or metastatic malignant neoplasm involving the stomach. "The CRKL gene is also known as an oncogene upregulated in cancer cells, specifically associated with lung and gastric cancer." (PMID 38203854, 2024). "The expression of CCR6 and CrkL is also significantly associated with metastasis, stage, and poor prognosis of gastric cancer." (PMID 32707869, 2020). "We conclude that CRKL protein is overexpressed in a subset of gastric cancers and is associated with CRKL amplification in gastric cancer." (PMID 22591714, 2012). "CRKL protein was overexpressed in 24.4% of the primary gastric cancers, and its level in the gastric cancer was associated with the gender and histopathology." (PMID 22591714, 2012). "The depletion of CrkL in SGC-7901 gastric cancer cells led to a significant decrease in cell proliferation, as well as a pronounced interruption of the cell cycle at the G0/G1 phase." (PMID 40362257, 2025). "In gastric cancer, CRKL was markedly correlated with clinicopathologic features, and inhibition of CRKL diminished gastric cancer cell proliferation." (PMID 38289488, 2024). "Knockdown of miR-429 in gastric cancer cells increased CRKL protein levels and promoted EMT through the Akt signaling pathway." (PMID 37894400, 2023). "CRKL is upregulated in many malignancies, such as gastric cancer, hepatocellular carcinoma, lung cancer, and cervical cancer, and correlates with a poor disease prognosis." (PMID 37894400, 2023). "In particular, both Crk and CrkL have been demonstrated to be important for tumor cell migration and invasion in colorectal cancer, glioblastoma, ovarian cancer, cervical cancer, gastric cancer, and hepatocellular carcinoma." (PMID 33801580, 2021). "Depletion of CRKL in a gastric cancer cell line resulted in impairment of SLC7A5 expression and suppression of cell motility." (PMID 33429909, 2021). "Crk knockdown and CrkL knockdown induced arrest of the cell cycle at G1 in synovial sarcoma and gastric cancer cells, respectively." (PMID 33801580, 2021). "CCL20/CCR6 induced gastric cancer EMT through the activation of the AKT pathway in response to CrkL; similar results were found with CCL21/CCR7 axis activated JAK2/STAT3 signaling pathways in promoting stemness of OSCC EMT progression." (PMID 34943853, 2021). "CT10 regulator of kinase like protein (CrkL) has been identified as a key regulator in EMT, and both CCR6 and CrkL are aberrantly expressed in gastric cancer specimens." (PMID 32707869, 2020). "MiR-335 promoted gastric cancer (GC) cell apoptosis by targetting CT10 oncogene homolog-like (CRKL)." (PMID 29217524, 2018). "By depleting CRKL in gastric cancer SGC-7901 cells, the SLC7A5 expression was impaired, and the invasion and migration of SGC-7901 cells were suppressed." (PMID 27846244, 2016). "The aim of this study is to investigate the regulating effect of CRKL, one of the critical genes involving with gastric cancer progression, on SLC7A5 expression." (PMID 27846244, 2016). "CRKL amplification was more frequently found in primary gastric cancers with high CRKL protein expression levels than in those with low CRKL expression levels." (PMID 22591714, 2012). "Our results should contribute to the establishment of CRKL-targeting therapy for a subset of gastric cancers in the future." (PMID 22591714, 2012). "We also showed that the CRKL protein can upregulate cell proliferation using the RNA-interference-mediated knockdown of CRKL in a gastric cancer cell line with CRKL amplification." (PMID 22591714, 2012). "An immunohistochemical analysis revealed that CRKL protein was overexpressed in 24.4% (88/360) of the primary gastric cancers that were analyzed." (PMID 22591714, 2012). "Our current findings suggest that CRKL has an important role in the development of a subset of gastric cancers and has the potential to be a molecular therapy target for gastric cancer." (PMID 22591714, 2012).